HNF4A (hepatocyte nuclear factor 4 alpha)
Diseases named in the same sentence as HNF4A in open-access papers (continued):
Sharing a sentence is not in itself a finding about the gene and the disease.
benign prostatic hyperplasia (1 paper, 2020). A non-cancerous nodular enlargement of the prostate gland. "Immunohistochemistry of HNF4α showed that epithelial cells in normal prostate and benign prostatic hyperplasia (BPH) tissues showed positive nuclear staining." (PMID 31695151, 2020).
bile reflux (1 paper, 2021). "Suppression of the HDAC6/HNF4α loop and restoration of miR-1 may be a promising approach for gastric IM in patients with bile reflux." (PMID 32705446, 2021).
bleeding disorder (1 paper, 2019). "Studies have shown that decreased expression of HNF4A is also correlate with bleeding disorder due to decreased expression of the blood coagulation factor VII." (PMID 31547152, 2019).
choroid plexus papilloma (1 paper, 2009). "In the past attempts to detect HNF4α DNA binding in a choroid plexus papilloma failed." (PMID 19575803, 2009).
coagulopathy (1 paper, 2025). "Dengue fever exacerbates coagulopathy in patients, particularly those with pre-existing coagulation disorders, by inducing thrombocytopenia and downregulating key coagulation factors I, V, X, and XIII through the NS1 protein’s suppression of HNF4α, worsening the overall coagulopathy." (PMID 40692953, 2025).
coinfection (1 paper, 2025). The simultaneous infection of a host by multiple pathogen species. "Although it is also well known that HNF4α promotes viral replication via binding to the HBV enhancers, little information is available about the role of vertebrate HNF4α in the regulation of host immune responses to control bacterial infection or bacterial-viral coinfections." (PMID 40920830, 2025). "This study demonstrates that piscine HNF4α contributes to host antibacterial and antiviral defense by inducing the expression and activities of caspase 3 and caspase 9, positioning it as a potential therapeutic target for bacterial, viral, and coinfection scenarios." (PMID 40920830, 2025). "Given the functional conservation of hnf4α between zebrafish and grass carp in A. salmonicida/GCRV-II single and co-infections, we used zfhnf4α knockout larvae to explore whether zfhnf4α modulates antimicrobial responses via interferons or inflammatory cytokines." (PMID 40920830, 2025).
colonic disease (1 paper, 2009). "The delayed manifestation of the clinical symptoms related to the colonic disease indicates that loss of Hnf4α involves complex mechanistically interactions that ultimately lead to the development of the disease." (PMID 19898610, 2009). "Thus, apoptosis and cell proliferation was increased in the long term in colon disease of Hnf4α mutant mice probably as a consequence to the inflammatory response." (PMID 19898610, 2009).
cyst (1 paper, 2012). A sac-like closed membranous structure that may be empty or contain fluid or amorphous material. "Analyzing kidney/body weight and cystic index between P19 and P21 in a set of 46 cre positive Pkd1cko/cko animals (8 Hnf4αcko/cko; 23 Hnf4αcko/wt; 15 Hnf4αwt/wt), our results suggest that the presence of HNF4α has a significant protective effect on cyst formation." (PMID 23209428, 2012). "Therefore, we perturbed the network map by inactivating Hnf4α in the context of Pkd1 inactivation and found that HNF4α in fact plays an important modulatory role in the early onset Pkd1 cyst model." (PMID 23209428, 2012). "Therefore, we speculate that the paucity of cortical cysts in the early stages of cyst formation, and the increased severity of cystic disease in double Hnf4α/Pkd1 knockout might reflect a protective role of HNF4α." (PMID 23209428, 2012).
cystinosis (1 paper, 2025). Cystinosis is a metabolic disease characterized by an accumulation of cystine inside the lysosomes, causing damage in different organs and tissues, particularly in the kidneys and eyes. "Indeed, loss of Hnf1a and Hnf4a expression has been implicated in the development of proximal tubular dysfunction, resulting in glycosuria and polyuria, which are hallmark features of cystinosis." (PMID 40917744, 2025).
diabetic retinopathy (1 paper, 2024). "Recently, HNF4A has been known to have protective roles in inflammation via anti-angiogenesis, where the knockout of HNF4A promotes diabetic retinopathy." (PMID 38672162, 2024).
Dyskinesia (1 paper, 2015). A movement disorder which consists of effects including diminished voluntary movements and the presence of involuntary movements. "Downregulation of HNF4A has been reported in blood from PD patients as a PD biomarker correlating with motor symptoms severity, whereas FOSL2 has been linked to dyskinesia, a major side effect in the DA substitutive treatment with L‐DOPA." (PMID 26516212, 2015).
embryonal tumors (1 paper, 2024). "The absence of HNF4A and other hepatic TFs may explain the low levels of hepatic markers in the embryonal tumors." (PMID 39567475, 2024).
familial hyperlipidemia (1 paper, 2010). An instance of hyperlipidemia (disease) that is caused by an inherited modification of the individual's genome. "HNF4A is also involved in the regulation of serum lipid levels and is linked to elevated serum cholesterol and triglyceride levels in Finnish combined familial hyperlipidemia patients." (PMID 20158877, 2010).
gastric diseases (1 paper, 2016). "Our data insinuates that, due to the dual receptor response to Hp infection composed by nuclear receptor HNF4α and its target IL-1R1, a combined therapeutic strategy might be more efficient in controlling NF-κB activation for Hp associated gastric diseases." (PMID 26870992, 2016).
germinoma (1 paper, 2020). A malignant germ cell tumor arising in the central nervous system. "While this particular sample showed higher expression of GATA6, FOXA2, or HNF4A and hypermethylation of RASSF1, RUNX3, HIC1, or APC, its methylation pattern was partially common to that of germinomas or ECs." (PMID 32999426, 2020).
gestational diabetes (1 paper, 2024). Carbohydrate intolerance first diagnosed during pregnancy. "The diagnosis of HNF1A/HNF4A-MODY is considerably less prevalent among individuals with presumed gestational diabetes." (PMID 39902162, 2024).
hearing loss (1 paper, 2018). "Stamatiou and Stankovic identified a number of molecules including HNF4A that are likely to be key mediators of genetic hearing loss through network and pathway analyses." (PMID 30005691, 2018). "Here, we report a case of FS caused by HNF4A mutation that presented with hearing loss." (PMID 30005691, 2018).
Hematochezia (1 paper, 2009). The passage of fresh (red) blood per anus, usually in or with stools. "Consistent with the similarity to the histopathology seen in patients with IBD, some of the Hnf4α mutant mice displayed a characteristic phenotype with relapsing episodes of hematochezia and rectal prolapse (data not illustrated)." (PMID 19898610, 2009).
hemophilia A (1 paper, 2017). The most common form of hemophilia characterized by spontaneous or prolonged hemorrhages due to factor VIII deficiency. "After 5 months of transplantation (Tx) of eGFP-expressing Lin- BMCs from female to hemophilia A (HA) male mice, the immuno-histochemical analysis of liver sections revealed the presence of donor-derived cells expressing hepatic markers, like albumin and HNF4α." (PMID 28328977, 2017).
Huntington disease (1 paper, 2012). Huntington disease (HD) is a rare neurodegenerative disorder of the central nervous system characterized by unwanted choreatic movements, behavioral and psychiatric disturbances and dementia. "Network 2 (tp.186d.nt2) consists of factors acting on Huntington's disease signaling (HTT), HNF4A and cAMP signaling." (PMID 22479328, 2012).
hydronephrosis (1 paper, 2021). Collection of urine in the renal pelvis that results in dilatation of the renal pelvis and calyces. "Of note, Hnf4a mutant mice exhibited at P14 overt non-obstructive hydronephrosis, probably due to the lack of reabsorption in PTs." (PMID 33737325, 2021).
hyperandrogenism (1 paper, 2024). Excessive secretion of androgens from the adrenal glands or gonads. "Oxidative stress hinders the production and release of SHBG by reducing the activity of HNF-4α, which could potentially play a significant role in the development of hyperandrogenism in PCOS." (PMID 38589892, 2024).
hyperthyroidism (1 paper, 2025). Overactivity of the thyroid gland resulting in overproduction of thyroid hormone and increased metabolic rate. "Weight loss, fasting, hyperthyroidism, or thyroid hormone treatment, growth hormone pulsatility promote hepatocyte nuclear factor 4 alpha (HNF-4α) activity, resulting in increased hepatic synthesis of the major SHBG fraction." (PMID 40427034, 2025).
hypertriglyceridemia (1 paper, 2022). A laboratory test result indicating elevated triglyceride concentration in the blood. "HNF4A also activated APOC3, which may contribute to hypertriglyceridemia." (PMID 35925965, 2022).
Hypocholesterolemia (1 paper, 2019). An decreased concentration of cholesterol in the blood. "Similarly, acute loss of liver Hnf4α in mice, generated by adenovirus expressing small hairpin RNA corresponding to Hnf4α, leads to hypocholesterolemia." (PMID 30483910, 2019).
injury (1 paper, 2025). Damage inflicted on the body as the direct or indirect result of an external force, with or without disruption of structural continuity. "Liver‐specific knockdown of HNF4α significantly abolished the BA regulatory activity and hepatoprotective effect of FGF1ΔHBS in INH and RIF‐induced liver injury mouse model." (PMID 39731358, 2025).
intestinal polyposis (1 paper, 2019). "HNF4α expression has been shown to be crucial for the survival of CRC cell lines in culture and during intestinal polyposis in mice." (PMID 31060309, 2019).
intrahepatic cholangiocarcinoma (1 paper, 2018). A carcinoma that arises from the intrahepatic bile duct epithelium in any site of the intrahepatic biliary tree. "Moreover, another study revealed that mutant IDH1 and 2, the most common genetic alterations found in intrahepatic cholangiocarcinoma, inhibit HNF4A expression, block hepatocyte differentiation and induce biliary cancer formation." (PMID 29899848, 2018).
keloid (1 paper, 2025). An irregularly shaped, elevated mark on the skin caused by deposits of excessive amounts of collagen during wound healing. "The most significant upstream regulators, consisting of genes or other small molecules observed experimentally to affect expression of keloid-associated genes, included HNF4A, beta-estradiol, and dexamethasone across all analyses." (PMID 40835838, 2025).
melanoma (1 paper, 2016). A malignant, usually aggressive tumor composed of atypical, neoplastic melanocytes. "It is unclear whether the reduced miR-7-5p levels observed in some melanomas can be explained by loss of HNF4α expression or activity." (PMID 27203220, 2016).
mucinous tumors (1 paper, 2021). "This process involves the increased expression of certain stomach‐restricted genes such as Hnf4α, Vsig1, Gkn3, Ctse and Onecut2 in Nanog‐deleted mucinous tumors." (PMID 33439550, 2021). "Gastric proteins HNF4α and GKN1 were increased in mucinous tumors as previously reported." (PMID 33439550, 2021).
myeloma (1 paper, 2020). "Among the genes uniquely expressed following Ix-treatment in resistant myeloma were RICTOR (activated), HNF4A, miR-16-5p (activated), MYCN (inhibited), and MYC (inhibited)." (PMID 32724061, 2020).
neonatal hyperinsulinism (1 paper, 2024). "Even though HNF-1A and HNF-4A are composed of different protein domains and exert specific gene regulatory functions, variants in the HNF1A and HNF4A genes lead to MODY forms of similar clinical phenotype (HNF1A-MODY and HNF4A-MODY, respectively) and are associated with neonatal hyperinsulinism." (PMID 38855865, 2024).
neutropenia (1 paper, 2018). A decrease in the number of neutrophils found in the blood. "In the discovery cohort, 18 genetic variations in genes encoding four NRs (HNF4α, PXR, PPARs, and VDR), one transcription factor (NF-κB), and one cytokine (TNF) emerged as significant (p < 0.05) predictors of severe neutropenia over the entire course of chemotherapy." (PMID 29706892, 2018).
oesophagitis (1 paper, 2017). "Further investigation will be required to establish the cause of HNF4α induction, and whether the HNF4α protein is found in oesophagitis." (PMID 27875772, 2017).
Osteopenia (1 paper, 2023). Osteopenia is a term to define bone density that is not normal but also not as low as osteoporosis. "In vivo, osteoblast-specific deletion of Hnf4α in healthy mice results in osteopenia." (PMID 37079387, 2023).
osteoporosis (1 paper, 2023). A condition of reduced bone mass, with decreased cortical thickness and a decrease in the number and size of the trabeculae of cancellous bone (but normal chemical composition), resulting in increased fracture incidence. "Prior to our study, a single report has found that HNF4α might be a central regulator of genes also involved in osteoporosis." (PMID 37079387, 2023).
polycystic ovary syndrome (1 paper, 2025). A disorder that manifests as multiple cysts on the ovaries. "Such susceptible individuals may include those with polycystic ovary syndrome (PCOS), endometriosis, disrupted gastrointestinal motility, as well as people carrying genetic defects (e.g., IL-10 or HNF4A deficiency)." (PMID 41488633, 2025).
severe combined immunodeficiency (1 paper, 2017). Severe combined immunodeficiency (SCID) comprises a group of rare monogenic primary immunodeficiency disorders characterized by a lack of functional peripheral T lymphocytes resulting in early-onset severe respiratory infections and failure to thrive. "Nonobese diabetic/severe combined immunodeficiency (NOD/SCID) mice injured by carbon chloride (CCl4) were then transplanted with control, HNF4α-overexpressing or HNF4α-suppressing hepatic oval cells." (PMID 28807057, 2017).
Syndromic (1 paper, 2023). "Syndromic disorders associated with impaired glucose metabolism and early-onset diabetes may manifest with CHI in early infancy as a common pattern (HNF4A, HNF1A microdeletion, EIF2S3)." (PMID 37065762, 2023).
urinary tract obstruction (1 paper, 2021). Blockage of the normal flow of contents of the urinary tract. "Without evidence of urinary tract obstruction, we further examined HNF1B, HNF4A and WT1 immunostainings on serial embryonic sections, focusing on glomeruli with different degrees of Bowman's capsule expansion." (PMID 33737325, 2021).
tumor (234 papers, 2006 to 2026). "Beyond its role in hepatic cell differentiation and regulation of key markers such as ALB and AFP, HNF4α is also important in attenuating cancer‐associated characteristics and suppressing tumor progression." (PMID 41244070, 2025). "Accordingly, HNF4A loss significantly induced tumour growth from the second week after cell inoculation." (PMID 39165427, 2024). "Transcriptomic analyses in bulk PDAC tumours revealed HNF4A loss, mainly in the squamous and pancreatic progenitor subtypes." (PMID 39165427, 2024). "HNF4α is linked to numerous signaling pathways that significantly contribute to tumor transformation, metastasis, inhibition of apoptosis, and promotion of proliferation." (PMID 38372868, 2024). "Expression of P1-/P2-promoter-driven nuclear HNF4α is significantly correlated with cytoplasmic β -catenin in colitis-associated tumor and sporadic CRC." (PMID 36249028, 2022). "For example, tumor-suppressive role has been suggested for HNF4A based on a rat model, but increased expression of a HNF4A transcript variant is associated with poor prognosis of HCC patients." (PMID 34302118, 2021). "HNF4α is associated with many signaling pathways that play an important role in tumor transformation, metastasis, inhibition of apoptosis, and promotion of proliferation." (PMID 33462379, 2021). "Their results also showed that overexpression of HNF4α in human GC tissue was associated with more advanced tumor stage and lymph node metastasis." (PMID 33462379, 2021). "Its role of tumor suppressor is underlined by the fact that HNF4α loss is determinant for both HCC CRC onset and progression." (PMID 30154449, 2019). "Both transcription factors, as well as the HNF4α target PK-L, were undetectable in FoxA1/2-deficient neoplasia." (PMID 30475207, 2018). "Since knockdown of HNF4A caused a reduction in ApoB and HNF1A expression, possibly loss of HNF4 reduces the expression of these genes and subsequently tumor growth is triggered." (PMID 29899848, 2018). "We explored the viral role in the inhibition of HNF4α expression, and consequent induction of tumor-promoting genes in HCV infection-associated HCC." (PMID 26157476, 2015). "HNF4A has been reported to be a tumor suppressor in hepatocytes, and loss of HNF4A is associated with increased proliferation, and increased tumor size and number in an induced hepatic tumor model." (PMID 26287733, 2015). "An important consequence of HNF4α depletion is the erosion of normal epithelial architecture and acquisition of mesenchymal markers, a hallmark of tumor progression." (PMID 26157476, 2015). "After stratifying patients into groups with high and low expression (relative to the mean expression of HNF4A in the tumor samples), we found that low HNF4A expression is associated with shorter survival in KIRC patients (log-rank p-value 0.007)." (PMID 25961905, 2015). "We also show that a transcription factor associated with hepatic development and tumor biology, HNF4A, is a prominent hub in the proteomic analyses." (PMID 22848702, 2012). "Loss of HNF4α may also promote tumor-associated inflammation through a microRNA-inflammatory feedback loop circuit." (PMID 41595461, 2025). "Various lncRNAs can associate with HNF4α to modulate tumor progression in different cancer types." (PMID 39199690, 2024). "HNF4A loss significantly induced, while HNF4A overexpression suppressed tumour growth." (PMID 39165427, 2024). "We propose that incorporating LEF1 and HNF4A into diagnostic staining panels could enhance tumor diagnosis, enabling a more precise tumor subtyping and correlations between molecular profiles of tumor and disease prognosis." (PMID 39567475, 2024). "Our analysis shows that the progression from premalignant conditions to tumour is accompanied by differences in the downregulation of genes associated with HNF4A activity and the immune system and upregulation of cell cycle genes, bringing about variability in patient outcomes." (PMID 38157373, 2023).